MMP1 (matrix metallopeptidase 1)
Diseases named in the same sentence as MMP1 in open-access papers (continued):
Sharing a sentence is not in itself a finding about the gene and the disease.
periodontitis (continued). "Besides MMP-8, decreased levels in gingival crevicular fluids after the effective treatment of periodontitis have also been observed for MMP-1, -9, -12, and -13." (PMID 37371608, 2023). "We previously reported that sIL-6R was detected at higher levels in the GCF of periodontitis sites than in healthy sites and that these molecules induce MMP-1 expression in the secondary response to IL-6 produced by IL-1β and indirectly activate intracellular signaling pathways in HGFs." (PMID 36834667, 2023). "Interestingly, our report shows that pregnant women with obesity and periodontitis expressed higher levels of Histatin-3 and Metalloproteinase inhibitor 1 (MMP1), with the latter being a protein uniquely expressed in OP." (PMID 36355174, 2022). "Therefore, because the regulation of MMP-1 and proinflammatory cytokines is important for the treatment of periodontitis, we demonstrated that downregulating matriptase inhibited the PG-LPS-induced MMP-1 and proinflammatory cytokine expression in HGFs." (PMID 36246974, 2022). "MMP-1 is a collagenase that is involved in extracellular matrix breakdown during periodontitis." (PMID 25823008, 2015). "Owing to the important role of MMP-1 in the pathogenesis of periodontitis, a variety of molecular epidemiological studies have been conducted to explore the association between MMP-1 polymorphisms and the susceptibility of periodontitis." (PMID 23527212, 2013). "However, a meta-analysis concluded that single nucleotide polymorphisms of MMP-1 (−1607 1G/2G, −519 A/G, and −422 A/T) were not related to periodontitis risk." (PMID 35454140, 2022). "However, as elevated MMP1 levels have also been associated with periodontitis, it must be ruled out that NIPP is not harmful to gingival cells and tissue." (PMID 35453639, 2022). "Similarly, lack of association between MMP-1 gene variants in terms of CP severity as well as smoking status and periodontitis risk was observed in the present meta-analysis and systematic review." (PMID 27194818, 2016). "In addition, periodontitis-affected gingival tissue express high levels of MMP-1 mRNA." (PMID 26859747, 2016). "First, an overview of clinical outcomes revealed that, even with the same genotype, the presence of a high variation in MMP-1 expression among periodontitis individuals could be due to additional influence of specific periodontopathogens and cytokine stimulation." (PMID 27194818, 2016). "NAMPT may contribute to periodontitis through upregulation of MMP-1 and CCL2 in PDL cells." (PMID 24058270, 2013). "In the chronic periodontitis group, there was a significant increase in high-glycoform EMMPRIN (HG-EMMPRIN) and active MMP-1 compared to healthy controls (p < 0.05)." (PMID 40075856, 2025). "In gingival fibroblasts cultured in vitro, the accumulation of AGEs may upregulate the expression of MMP-1, and the RAGE/NF-κB pathway is involved in the metabolism of MMP-1, and thus both pathways may be important for the development of diabetes-associated periodontitis." (PMID 40004956, 2025). "Lastly, the host enzymes MMP-1 and MMP-9 were statistically significantly (p ≤ 0.003) increased at both periodontitis versus gingivitis sites and gingivitis versus healthy sites." (PMID 41303313, 2025). "For example, in the OM, pathogens like Prevotella intermedia and Fusobacterium nucleatum induce the expression of MMP-1, MMP-8, and MMP-9 during periodontitis and dental caries." (PMID 40332093, 2025). "Similar outcomes were revealed in a study by Kubota and colleagues: in periodontitis-affected gingival tissue, the expression of MMP (MMP-1, MMP-3, and MMP-8) mRNA was higher in the diseased group than in the control group." (PMID 38474009, 2024). "The authors concluded that several MMPs, particularly MMP-1, MMP-2, MMP-9, and MMP-13, are involved in gingival ECM degradation during periodontitis." (PMID 38474009, 2024).
periodontitis (continued). "Salivary levels of miR-1246 in patients with chronic periodontitis were positively correlated with the levels of IL-1β, IL-6, IL-17, TNF-α, MMP-1, MMP-8, TIMP-1, PLI, GI, PD, and AL (P < 0.05)." (PMID 35942384, 2022). "The salivary levels of miR-1246, IL-1β, IL-6, IL-17, TNF-α, MMP-1, MMP-8, and TIMP-1 and the periodontal indexes PLI, GI, PD, and AL in the chronic periodontitis group were significantly higher than those in the healthy control (P < 0.05)." (PMID 35942384, 2022). "The results of this study also showed a positive correlation between MMP-1, MMP-8, TIMP-1 levels, and miR-1246 levels in the chronic periodontitis group, suggesting that increased miR-1246 expression may be associated with the destruction of periodontal tissues by proteases in chronic periodontitis." (PMID 35942384, 2022). "Elevated levels of MMP-1 have been found in GCF and gingival tissue samples from periodontitis sites compared to periodontally healthy sites." (PMID 33513808, 2021). "The sensor is sensitive also to cleavages by MMP-1, MMP-13, and MMP-9 present and upregulated in the diseased periodontitis and peri-implantitis tissue and oral fluids." (PMID 30154936, 2018). "However, in our study we could not only find any significant association between MMP-1 −1607 1G/2G polymorphism and periodontitis risk, but also failed to associate MMP-1 −519 A/G and −422 A/T SNPs with the susceptibility to periodontitis." (PMID 27194818, 2016). "And based on previous studies, dramatically elevated levels of MMP-1, MMP-2, MMP-3, MMP-8, and MMP-9 have been detected in gingival crevicular fluid, peri-implant sulcular fluid, and gingival tissue of periodontitis patients." (PMID 27194818, 2016). "Several studies have revealed that MMP-1 levels are increased in GCF and human gingiva from periodontitis patients." (PMID 24058270, 2013). "Furthermore, ELISA analysis of periodontitis-related markers in the blood showed that W. cibaria CMU exhibited significant preventive ability to induce periodontitis in TNF-α, IL-6, MMP-1, and MMP-9 categories." (PMID 40007939, 2025). "MMP-1 and MMP-3 have been demonstrated to play an important role in periodontitis." (PMID 37445663, 2023). "Levels of sCD30/TNFRSF8, IFN-α2, IL-19, IL-26, MMP-1, gp130/sIL-6Rß, and sTNF-R1 were significantly higher in serum or GCF, and April/TNFSF13 was significantly higher in serum and saliva samples in moderate/severe periodontitis." (PMID 31072030, 2019). "In GCF samples, significantly (p < 0.05) higher levels of IFN-α2, IL-19, IL-26, MMP-1 and sTNF-R1 were observed in RA patients with moderate/severe periodontitis compared to corresponding RA subjects with no/mild periodontitis." (PMID 31072030, 2019). "In addition to this, MMP-1, MMP-2, MMP-10, and MMP-12 were also observed to be significantly increased in patients with OSCC compared to healthy patients and patients with benign oral masses (OBM) and mild chronic periodontitis (CPD)." (PMID 33892690, 2021). "Therefore, unraveling the regulation of MMP-1 and MMP-3 may contribute to the development of treatments for periodontitis." (PMID 34504537, 2021). "Furthermore, a previous study also showed that myricetin decreased the mRNA expression and enzyme activity of matrix metalloproteinase-1 (MMP-1), MMP-2, and MMP-8, which were involved in the inflammatory progression in periodontitis in the human gingival fibroblasts (HGF)." (PMID 27011174, 2016). "However, in the rat, MMP-13 is analogous to the constitutive collagenase, MMP-1, in humans and likely plays a role in physiologic turnover of collagen rather than the pathological degradation of collagen during periodontitis." (PMID 25104884, 2014). "There were only 2 studies for MMP-1-519 A/G, neither found any relationship with periodontitis." (PMID 23527212, 2013).
periodontitis (continued). "This study evaluated the gene expression of IL-1ß, IL-6, TNF-α, MMP-1, MMP-2, MMP-8, MMP-9, TIMP-1, and TIMP-2 in the gingival tissue of individuals with periodontitis or peri-implantitis compared to individuals without periodontal or peri-implant disease." (PMID 33291232, 2020). "In the present study, the levels of sCD30 (TNFRSF8), sTNF-R1, gp130 (sIL-6Rß), IL-19, IL-26 and MMP-1 were increased in serum, saliva or GCF samples from subjects with moderate/severe periodontitis as compared to no/mild disease." (PMID 31072030, 2019). "However, Gonçalves and colleagues revealed that MMP transcripts (for MMP-1, MMP-2, MMP-9, and MMP-13) found in gingiva samples were not significantly different in patients affected by gingivitis, chronic periodontitis, and aggressive periodontitis." (PMID 38474009, 2024).
gastric cancer (56 papers, 2002 to 2025). A primary or metastatic malignant neoplasm involving the stomach. "A host of studies also demonstrated that MMP-1 gene rs1799750 polymorphism was related to cancer susceptibility, such as leukemia and gastric cancer." (PMID 30177524, 2018). "In biopsies of H. pylori-associated gastritis and gastric cancer MMP-1, -2, -7, -8, -9, -10, -11, -12, and MMP-14 were upregulated." (PMID 28398251, 2017). "In in vitro invasion assays H. pylori induced migration across a collagen matrix was critically dependent on MMP-1 activity which underlines its importance in metastasis of gastric cancer." (PMID 28398251, 2017). "Distribution of MMP-1 paired loci polymorphisms with increasing order of variant alleles and association with the gastric cancer risk." (PMID 24505369, 2014). "While the importance’s of other SNPs in the MMP-1 promoter have not yet been studied in gastric cancer, our aim was to investigate MMP-1 gene promoter polymorphisms and gastric cancer susceptibility in eastern Indian population." (PMID 24505369, 2014). "Association between the genotypes of MMP-1 SNPs and clinicopathological characteristics of gastric cancer patients." (PMID 24505369, 2014). "For MMP-1.3 polymorphism, patients carrying combination of TA and TT genotypes were at more risk of lower stomach cancer (lower & middle body, antrum and pylorus of stomach) (p = 0.043, OR = 2.18, CI = 1.03–4.64)." (PMID 24505369, 2014). "Association of increasing order of MMP-1 polymorphic variant alleles in haplotypes with Lower stomach gastric cancer risk." (PMID 24505369, 2014). "This study examined the associations between individual SNPs or haplotypes in MMP-1 and susceptibility, clinicopathological parameters and prognosis of gastric cancer in a large sample of the Han population in northern China." (PMID 22655095, 2012). "Then, SPSS software, Haploview 4.2 software, Haplo.states software and THEsias software were used to estimate the association between individual SNPs or haplotypes of MMP-1 and gastric cancer susceptibility, progression and prognosis." (PMID 22655095, 2012). "In conclusion, this study evaluated polymorphisms of the MMP-1 gene in gastric cancer with a MALDI-TOF MS method and archived FFPETs in a large northern Chinese case-controlled cohort." (PMID 22655095, 2012). "This study evaluated polymorphisms of the MMP-1 gene in gastric cancer with a MALDI-TOF MS method in a large northern Chinese case-controlled cohort." (PMID 22655095, 2012). "Additionally, expression of ASPN, which encodes an extracellular substrate in gastric cancer, and other inflammatory response genes (Mmp‐1, Mmp‐3) was increased in both CEFs and CAFs (green box)." (PMID 34379869, 2022). "For example, in gastric cancer, the MMP1 and MMP2 increased expression is related to the loss of E-cadherin expression, thereby, leading cancer proferliation and metastasis.MMP-3 and MMP-7 have association with the development of Helicobacter pylori-related gastric cancer." (PMID 34422902, 2021). "Gastric cancer has been linked to four matrix metalloproteinases (MMPs) (MMP-1, -2, -7 and -9)." (PMID 34885950, 2021). "Analysis of association between MMP-1 SNPs and the risk of occurrence of gastric cancer." (PMID 24505369, 2014). "MMP-1.3 polymorphism which shows a positive significance (p = 0.021) for regional lymph node metastasis having a combination of TA and TT genotype, suggests that the T allele has a detrimental effect on gastric cancer progression and early metastasis." (PMID 24505369, 2014). "Associations between genotype distributions of seven SNPs in MMP-1 and the risk of gastric cancer." (PMID 22655095, 2012). "Contradictory to MMP-1.3 polymorphism, patients carrying a combination of TC and CC genotypes gave protection against regional lymph node metastasis (p = 0.026, OR = 0.34, CI = 0.13–0.88) in addition to distant metastasis (p = 0.061, OR = 0.49, CI = 0.24–1.03) of gastric cancer." (PMID 24505369, 2014).
gastric cancer (continued). "Matrix metalloproteinase-1 (MMP1), a member of the MMP family, is associated with poor survival outcomes in breast, prostate, and gastric cancers because of its increased expression 22-23." (PMID 39629135, 2024). "It has also been reported to increase MMP-1 expression and enhance invasion of gastric cancer cells." (PMID 37055381, 2023). "For example, the downregulation of MMP1 inhibited invasion and migration in gastric cancer and cervical cancer." (PMID 36105241, 2022). "Interferon regulatory factor 2 inhibits gastric cancer invasion and migration by downregulating MMP1." (PMID 34445346, 2021). "Increased expression levels of Galectin-3 and MMP-1 were also found in gastric cancer cells, with similar effects of Galectin-3 on MMP-1." (PMID 32455781, 2020). "The MMP-1-positive rate in patients with gastric cancer, metastatic gastric cancer and chronic gastritis was 78.8% (63/80), 95.0% (19/20) and 25.0% (10/40), respectively." (PMID 25120597, 2014). "Diffuse types of gastric cancer are usually characterized by an abundant deposition of collagen fibers, possibly requiring higher levels of MMP-1 expression for proper tissue remodeling of the microenvironment." (PMID 24505369, 2014). "Expression of matrix metalloproteinase-1 (MMP-1), an interstitial collagenase, plays a major role in cellular invasion during development of gastric cancer, a leading cause of death worldwide." (PMID 24505369, 2014). "In this study, in order to determine the effect of H. pylori infection on gastric cancer, the associations among H. pylori infection, the expression of MMP-1 and MMP-10 and the invasion and metastasis of gastric cancer were investigated." (PMID 25120597, 2014). "The study demonstrated the putative association of MMP-1.3, MMP-1.4, and MMP-1.5 polymorphisms with the risk of lower stomach tumor formation in gastric cancer." (PMID 24505369, 2014). "Cytokines, such as interleukin-1 (IL-1), influence the expression levels of MMP-1 and act as growth stimulators correlating with liver metastasis of gastric carcinoma." (PMID 24505369, 2014). "Our findings are consistent with reports that MTAP expression in gastric carcinoma cells inhibits migration in a wound-healing assay, and that inhibition of MTAP causes increased expression of MMP-1 and MMP-9 in a human hepatocellular carcinoma cell line." (PMID 25387827, 2014). "In conclusion, the present study demonstrates for the first time that the loss of HIF-1α contributes to the development of aggressive peritoneal dissemination by upregulating MMP-1 in gastric cancer cell lines." (PMID 23181099, 2012). "f) Galectin-3, PAR-1, and MMP-1 are highly expressed and co-localized in malignant tissues from gastric cancer patients." (PMID 21966428, 2011). "Clearly, the over-expression of MMP-1 can increase gastric cancer cell invasion activity by blocking cell to cell and cell to matrix interactions by ECM degradation." (PMID 21966428, 2011). "We examined the expression levels of Galectin-3, PAR-1, and MMP-1 in gastric cancer patient tissues and also the effects of silencing these proteins with specific siRNAs and of over-expressing them using specific lenti-viral constructs." (PMID 21966428, 2011). "We also determined the expression levels of galectin-3, PAR-1 and MMP-1 in malignant tissues from gastric cancer patients for clinical correlations between these proteins in human specimens." (PMID 21966428, 2011). "As expected, MMP-1 over-expression increased the invasion potential of gastric cancer cells, and PAR-1 silencing significantly reversed this increase (p<0.001)." (PMID 21966428, 2011). "We determined the mRNA and protein expression levels of galectin-3, PAR-1 and MMP-1 in normal and malignant tissues from 20 gastric cancer patients, then employed RT-PCR using an image J analyzer." (PMID 21966428, 2011).